PINK1 (PTEN induced kinase 1)
Diseases named in the same sentence as PINK1 in open-access papers (continued):
Sharing a sentence is not in itself a finding about the gene and the disease.
Parkinson disease (continued). "Two key proteins are crucial for mitochondrial quality control machinery: mitochondrial PTEN-induced putative kinase 1 (PINK1) and cytosolic ubiquitin E3 ligase Parkin, and intriguingly, mutations of both of them are linked to familial forms of Parkinson’s disease." (PMID 38397838, 2024). "Based on the hypothesis that idiopathic and Mendelian PD share common underlying disease pathomechanisms, Soutar and co-workers sought to investigate whether Parkinson's disease risk GWAS candidates regulate the PINK1/Parkin-dependent mitophagy process." (PMID 38368938, 2024). "Parkinson’s disease is often associated with dysfunction in the PINK1–Parkin mitophagy pathway." (PMID 38203389, 2023). "The PINK1 gene mutation, responsible for an early onset of Parkinsonism, serves as a good example." (PMID 37108382, 2023). "Moreover, other studies have found that the mitochondrial damage caused by abnormal transport of PINK1 into mitochondria mediated by Tom70 is a key factor in the occurrence and development of Parkinson's disease." (PMID 38093274, 2023). "Therefore, the detection of mutations in mitochondrial ND5 indicate a co-existence with known ALS-causing genes as it has been shown for ND5/6 and Parkinson’s disease (PD)-related mutations in PINK1." (PMID 37507754, 2023). "COA7 gene variants may have caused parkinsonism in this case because mitochondrial function-related genes, such as parkin and PINK1, are known causative genes in some familial Parkinson’s diseases." (PMID 37264311, 2023). "Variants in PINK1 cause an AR, early onset form of parkinsonism (PARK6, OMIM# 605909)." (PMID 36875645, 2023). "PINK1 mutations are also associated with a recessive type of parkinsonism." (PMID 37240432, 2023). "The anti-viral immune regulators STING (STimulator of INterferon Genes) and NF-kB have been indicated in mammalian studies to respond to unmitigated mitochondria damage linked to mutations in quality control pathways such as the Parkinson’s Disease-associated Pink1/Parkin pathway." (PMID 37440574, 2023). "For example, one reason for Parkinson’s disease may be the mutations in Pink1/Parkin, which mediate mitofusin degradation, leading to the accumulation of damaged mitochondria and eventually excessive accumulation of ROS, resulting in cell killing." (PMID 37259422, 2023). "In addition, MUL1 pathway activation also compensate for loss of PINK1 and/or Parkin in some models of Parkinson’s disease." (PMID 37410705, 2023). "Mutations in PINK1 and Parkin lead to early onset Parkinson’s disease (PD)." (PMID 37440574, 2023). "PINK1 and Parkin-mediated mitophagy is the most extensively studied form of mitophagy, which has been linked to the pathogenesis of neurodegenerative disorders, including Alzheimer’s disease, Parkinson’s disease, and amyotrophic lateral sclerosis." (PMID 36379251, 2022). "The PINK1 (or PARK6) gene was identified to be linked to Parkinson’s disease (PD) for the first time by linkage analysis of consanguineous families with early-onset autosomal recessive PD and is recently reported as one of the most commonly mutated genes in early onset PD." (PMID 35968372, 2022). "Subsequently, a dystonia‐parkinsonism gene panel revealed homozygous p.L347P variants in PINK1." (PMID 35844286, 2022). "PINK1/parkin is the main pathway that mediates mitochondrial autophagy, and mutations of PINK1 and parkin cause abnormal morphological and functional mitochondrial accumulation causing substantia nigra neurodegeneration and early-onset Parkinson's disease." (PMID 36164446, 2022). "Namely, loss of PINK1-dependent phosphorylation of ParkinSer65 leads to human Parkinsonism." (PMID 36303604, 2022). "Autosomal recessive mutations in the PINK1 gene are causal for Parkinson's disease (PD)." (PMID 35042401, 2022).
Parkinson disease (continued). "This is because the most common onset age for clinic symptoms of patients with PINK1 mutations is between 30 and 40 years, though a homozygous missense mutation was found to cause the earliest onset parkinsonism in a 5-year-old boy." (PMID 34800266, 2022). "Interestingly, the role of Pink1 has been widely studied in Parkinson’s disease since mutations in the PINK1 gene were identified in 2004 as a cause of early-onset Parkinson’s disease." (PMID 35682755, 2022). "However, two of three patients carrying both a parkin and a PINK1 mutations have been reported to have schizophrenia, and patients with both mutations are younger at onset of Parkinsonism than those with the same parkin mutation alone." (PMID 35698464, 2022). "Resolving this emerging interplay between immunity, mitochondrial signalling and redox metabolism may finally triangulate the pathomechanism of PINK1/Parkin-associated Parkinsonism." (PMID 36303604, 2022). "Genetic mutations of PINK1 and Parkin cause autosomal recessive early-onset Parkinson’s disease." (PMID 33888730, 2021). "The importance of mitophagy in the pathogenesis of neurodegenerative diseases is supported by the identified mutations of proteins involved in mitophagy—primarily PINK1 and parkin in Parkinson’s disease, optineurin and TBK1 in amyotrophic lateral sclerosis, and p62/SQSTM1 in frontotemporal dementia." (PMID 34638589, 2021). "Pathogenic variants in PINK1 cause early-onset Parkinson’s disease." (PMID 34893635, 2021). "Presenilins-associated rhomboid-like protein, mitochondrial (PARL) is a mitochondrial protease that cleaves PINK1, implicated in Parkinson’s disease and decreased activity could be associated with increased mitophagy through Parkin." (PMID 33986742, 2021). "Accumulation of defective mitochondria and impaired mitophagy have been widely implicated in many neurodegenerative diseases, and loss-of-function mutations of PINK1 and Parkin, two key regulators of mitophagy, are amongst the most common causes of heritable parkinsonism." (PMID 34489512, 2021). "It has been reported that additional monogenic forms of Parkinson’s may interplay with the PINK1/Parkin pathway including the Asp620Asn (D620N) mutation of the retromer-associated VPS35 gene." (PMID 34767452, 2021). "Loss of PINK1 function causes autosomal recessive early-onset Parkinson’s disease (PD)." (PMID 34686591, 2021). "PINK1 is a serine/threonine kinase that was initially linked to the pathogenesis of a familial form of Parkinson’s disease, and its loss-of-function mutations cause dopaminergic neuron mitochondrial calcium overload, which makes cells particularly vulnerable to injury." (PMID 33957982, 2021). "Mutations in PINK1 and Parkin are involved in rare familial cases of Parkinson’s disease (PD)." (PMID 32671064, 2020). "Mutations in PINK1 seem to play an important role in the pathogenesis of Parkinson’s disease." (PMID 33029756, 2020). "In addition, in zebrafish, loss of Nipsnap1—a mitochondrial matrix protein involved in PINK1/Parkin-independent mitophagy and highly expressed in mDANs—caused Parkinson's hallmarks." (PMID 33224433, 2020). "In Parkinson’s disease (PD), mitophagy is declined by the PINK1 mutation." (PMID 33292250, 2020). "Pink1, Parkin and Fbxo7, three autosomal recessive familial genes of Parkinson’s disease (PD), have been implicated in mitophagy pathways for quality control and clearance of damaged mitochondria, but the interplay of these three genes still remains unclear." (PMID 33291077, 2020). "In addition, the proteolytic activity of HtrA2 is affected by PINK1, another protein whose dysfunction is linked to Parkinson’s disease." (PMID 33227899, 2020). "Mutations in PINK1 and Parkin cause mitochondrial dysfunction and recessive Parkinson’s disease." (PMID 32585989, 2020). "Indeed, mutations in PINK1 and Parkin delay the removal of Miro1 from damaged mitochondria and cause Parkinson’s disease." (PMID 33374314, 2020).
Parkinson disease (continued). "Indeed, the role of calcium in the etiology of Parkinson’s disease has been extensively studied and, as an example, PINK1-associated Parkinson’s disease is caused by neuronal vulnerability to calcium-induced cell death." (PMID 32326436, 2020). "In addition, the loss of VPS13C functioning in early-onset forms of Parkinson disease was recently detected to aggravate PINK1/Parkin-dependent mitophagy." (PMID 31159836, 2019). "Furthermore, in Parkinson’s disease-associated mitochondrial dysfunction model with reduced dopamine production (PINK1-deficiency mice), the SN DA neurons display hyperexcitability in vivo with irregular firing patterns in vitro." (PMID 30766478, 2019). "The limited data available for SNCA and PINK1 mutations highlight the critical unmet need for large, multicenter studies aimed at characterizing the natural pattern of disease progression associated with rare genetic variants of Parkinson disease." (PMID 30707228, 2019). "Disruption in autophagy processes has been implicated in other neurodegenerative conditions such as Parkinson's disease, in which mutations in PINK1 and Parkin are believed to function in a common pathway to promote defective mitochondrial clearance via autophagy." (PMID 31160356, 2019). "Interestingly, Parkinson disease patients, who have mutated PINK1 in neurons, have decreased BCAA serum levels associated with an increase in the clinical severity of the disease." (PMID 31681280, 2019). "Mutations in the genes for PINK1 and parkin cause Parkinson’s disease." (PMID 29809156, 2018). "PINK1 mutation causes an autosomal recessive and early onset PD (Parkinson's disease)." (PMID 30595797, 2018). "The Parkinson's disease‐associated proteins Parkin and PINK1 are involved in the ubiquitination of Mfn2 on damaged mitochondria, which promotes local fission of the mitochondrial network thereby segregating damaged mitochondria for autophagic clearance (Ziviani, Tao & Whitworth, 2010)." (PMID 29068134, 2018). "Our current findings are particularly intriguing in the context of Parkinson disease because two other proteins implicated in familial Parkinson disease, parkin and phosphatase and tensin homolog induced putative kinase 1 (PINK1), play important roles in mitochondrial dynamics and mitophagy." (PMID 30571694, 2018). "Furthermore, PK molecular interplay with PTEN-induced kinase 1 (PINK1), a serine threonine kinase also involved in recessive cases of Parkinson’s disease, is considered to underlie the mitophagy process." (PMID 30697141, 2018). "Alterations in the supramolecular architecture of respiratory complexes were reported in rat cortex during aging; in an animal model of severe heart failure; in fibroblast from Parkinson’s disease patients harboring Pink1 mutations and in neuronal cultures from Pink1 and DJ1 KO mice." (PMID 29861458, 2018). "Mutations in PINK1 and Parkin lead to autosomal recessive forms of Parkinson’s disease (PD)." (PMID 28322724, 2017). "PINK1 deficiency causes the autosomal recessive PARK6 variant of Parkinson’s disease." (PMID 28768533, 2017). "Early onset Parkinson’s disease is caused by variants in PINK1, parkin, and DJ-1." (PMID 28962651, 2017). "Loss-of-function mutations in PINK1 or PARKIN are associated with early-onset Parkinson’s disease." (PMID 29290944, 2017). "The early onset of Parkinson disease may be caused by PINK1-mediated selective death of nerve cells." (PMID 27270507, 2016). "We report in this study a novel homozygous missense mutation p.L539F in PINK1 gene that could be pathogenic in a Moroccan consanguineous patient and extended the phenotypic spectrum of PINK1-associated Parkinsonism." (PMID 27413743, 2016). "Interestingly, distinct Rab family members have also been recently shown to be phosphorylated by the mitochondrial membrane protein kinase termed PTEN-induced putative kinase 1 (PINK1), which is itself also implicated in Parkinson's disease." (PMID 27621483, 2016).
Parkinson disease (continued). "Mutations in PINK1 or Parkin are the leading cause of parkinsonism." (PMID 26569220, 2015). "Several recent reports have demonstrated multiple means by which the defects associated with PINK1 deficiency can be alleviated, suggesting strategies to improve PINK1 function in patients with PINK1 loss-of-function mutations, but also in Parkinson’s patients with an intact mitophagy pathway." (PMID 25857750, 2015). "Mutations in Parkin and PINK1 cause an inherited early-onset form of Parkinson's disease." (PMID 26254305, 2015). "PINK1 mutations are linked to Parkinson disease (PD) and mostly result in loss of kinase activity." (PMID 24847206, 2014). "Mutations in PINK1 and Parkin are associated with early-onset Parkinson's disease." (PMID 24647965, 2014). "Our results provide new insights into the ubiquitination-dependent regulation of the Miro-mediated mitochondrial transport machinery by PINK1/Parkin and also suggest that disruption of this regulation may be implicated in Parkinson disease pathogenesis." (PMID 24671417, 2014). "We wanted to test whether GA and DL can rescue a mitochondrial defect caused by loss of other Parkinson's genes, i.e. PINK1 and Parkin." (PMID 25063200, 2014). "Mutations of Parkin and Pink1 are associated with familial forms of Parkinson's disease (PD)." (PMID 24949430, 2014). "DJ-1 mutations, which result in early-onset parkinsonism, may also regulate PINK1-dependent parkin translocation to depolarized mitochondria." (PMID 25061481, 2014). "Most cases have no obvious genetic cause, but around 15% of people with the disease have a close relative who also has the disease, and mutations in the genes encoding two proteins—PINK1 and Parkin—have been identified as prime suspects in familial Parkinson disease." (PMID 24569479, 2014). "Moreover, two genes, PINK1 and PARK2, found to link to Parkinson’s disease from genetic linkage studies encode protein PINK1 and Parkin." (PMID 24926233, 2014). "The role of mitophagy in Parkinson's disease has been an area of interest following observations that the protein kinase PINK1 and E3 ubiquitin ligase Parkin, both mutated in early onset forms of Parkinson's disease, act to induce mitophagy on mitochondrial membrane depolarization." (PMID 24176932, 2013). "Likewise, Parkinson’s disease-associated gene products (Parkin and PINK1) can not only influence the morphology of mitochondria, but also regulate mitochondrial degradation by mitophagy and possibly the transport of mitochondria in axons." (PMID 22806564, 2013). "Muscle degeneration, motor defects and the shorter lifespan of Drosophila PINK1 (dPINK1)-deficient flies, all of which appear to mimic Parkinson’s disease and to be attributed to mitochondrial degeneration, were suppressed in the double mutants deficient in both dPINK1 and dPGAM5." (PMID 23443160, 2013). "Recent findings indicate that parkin and the phosphatase and tensin homolog-induced putative kinase protein 1 (PINK1), which have been implicated in the pathogenesis of neurodegenerative diseases such as Parkinson’s disease, also regulate mitophagy and function to maintain mitochondrial homeostasis." (PMID 23267366, 2012). "Mutations in the PINK1 gene cause an autosomal recessive form of Parkinson's disease." (PMID 22662171, 2012). "Thus, although mutations in PINK1 and Parkin have been associated with neurodegeneration in Parkinson’s disease, further work is needed to clarify if the PINK1/Parkin pathway regulates damage-induced mitophagy in neurons." (PMID 23267366, 2012). "However, the protective effect of dPGAM5 found here was rather unexpected, as we had recently noted that dPGAM5 acts as an exacerbating factor in the Drosophila model of Parkinson's disease induced by PINK1 mutation." (PMID 22347370, 2012).
Parkinson disease (continued). "Loss of PINK1 function causes mitochondrial dysfunction, increased reactive oxygen species production and calcium dysregulation, which increases susceptibility to neuronal death in Parkinson's disease." (PMID 22662171, 2012). "In the literature, the youngest age of the onset of Parkinson's disease in patients harbouring homozygous PINK1 mutations is approximately 10 (A217D mutation), suggesting that at least a decade of PINK1 inhibition is required before Parkinson's disease symptoms develop." (PMID 22645651, 2011). "We have also, for the first time, been able to investigate the effect of Parkinson's disease-associated PINK1 missense mutations, and found that nearly all those located within the kinase domain, as well as the C-terminal non-catalytic region, markedly suppress kinase activity." (PMID 22645651, 2011). "The function of PINK1 remains poorly understood, although, in mammalian cells, several studies suggest that PINK1 controls another Parkinson's disease-associated enzyme, namely the parkin E3 ligase, by recruiting it to the mitochondrial membrane through an as-yet-undefined mechanism." (PMID 22645651, 2011). "PINK1 and Parkin mutations cause recessive Parkinson's disease (PD)." (PMID 21408142, 2011). "We determined the effects of Parkinson's disease-associated mutations on PINK1 catalytic activity by selecting 14 homozygous or compound heterozygous missense mutations that lead to early-onset Parkinson's disease in which the disease-associated amino acid residue is conserved in TcPINK1." (PMID 22645651, 2011). "Mutations in the PINK1 or Parkin genes lead to an inherited form of Parkinson disease." (PMID 20126261, 2010). "Mutations in PINK1 and Parkin cause familial, early onset Parkinson's disease." (PMID 21151574, 2010). "We find that patient mutations in PINK1 and Parkin disrupt the PINK1/Parkin mitochondrial turnover pathway at distinct steps, consistent with the potential relevance of this pathway for the development of Parkinson disease." (PMID 20126261, 2010). "Mutations found in PINK1 in early onset cases maybe the second most common mutation after Parkin to induce parkinsonism." (PMID 19721815, 2009). "Mutations in PRKN are a common cause of autosomal recessive early-onset parkinsonism, however mutations in PINK1 and DJ-1 have also been reported as associated with this type of parkinsonism, although only five causative mutations have been described in the latter." (PMID 18211709, 2008). "We identified two novel substitutions in the PINK1 serine/threonine kinase domain with the P416R as probable and the S419P as possible putative pathogenic mutation and the genetic cause of young-onset parkinsonism in two families." (PMID 19087301, 2008). "However, we cannot completely exclude a possible effect of the A340T polymorphism in combination with supplementary mutations within PINK1 or in other genes affecting parkinsonism." (PMID 19087301, 2008). "Additionally, both Cluster #5, "Neuronal Damage" and Cluster #6, "Targeting Mitophagy" are influenced by "Pink1-associated Parkinson's Disease" and "E3 Ubiquitin Ligase Parkin."This underscores the importance of Pink1 and Parkin research in understanding neuronal damage and mitophagy targeting." (PMID 41267150, 2025). "In addition, mutations in PINK1 have been linked to the occurrence of early onset Parkinsonism, and an increase in PINK1 protein might be an intrinsic protective mechanism to limit cellular death." (PMID 37691228, 2024). "LONP1 and CLPXP improve PD-related phenotypes, respectively, by degrading PINK1 and parkinson disease protein 7, which are involved in the pathological process of PD, and reducing the accumulation of α-synuclein variant A53T." (PMID 39164792, 2024).